MIR302C (microRNA 302c)
Synonyms: hsa-mir-302c; MIRN302C; mir-302c
Gene: MicroRNA gene on chromosome 4 (112,648,363 to 112,648,430, reverse strand). Ensembl gene ENSG00000199102.
Gene Ontology:
Biological process: miRNA-mediated post-transcriptional gene silencing
Cellular component: RISC complex
Homologues: Orthologues: chimpanzee ptr-mir-302c (100% identical), macaque mml-mir-302c (100% identical), dog MIR302C (99% identical), guinea pig MIR302C (93% identical), mouse Mir302c (93% identical), tropical clawed frog xtr-mir-302 (71% identical). Paralogues in human: MIR302D (81% identical), MIR302B (72% identical), MIR302A (71% identical).